CENPW (centromere protein W)
Description:
Component of the CENPA-NAC (nucleosome-associated) complex, a complex that plays a central role in assembly of kinetochore proteins, mitotic progression and chromosome segregation (By similarity). The CENPA-NAC complex recruits the CENPA-CAD (nucleosome distal) complex and may be involved in incorporation of newly synthesized CENPA into centromeres (By similarity). Part of a nucleosome-associated complex that binds specifically to histone H3-containing nucleosomes at the centromere, as opposed to nucleosomes containing CENPA. Component of the heterotetrameric CENP-T-W-S-X complex that binds and supercoils DNA, and plays an important role in kinetochore assembly. CENPW has a fundamental role in kinetochore assembly and function. It is one of the inner kinetochore proteins, with most further proteins binding downstream. Required for normal chromosome organization and normal progress through mitosis.
Synonyms: CENP-W; C6orf173; CUG2
Tractability: PROTAC: ubiquitination databases record sites on it.
Gene: Protein-coding gene on chromosome 6 (126,340,115 to 126,348,875, forward strand). Ensembl gene ENSG00000203760.
Subcellular location: Nucleus; Chromosome, centromere; Chromosome, centromere, kinetochore; Nucleus matrix; Nucleus, nucleolus
Subcellular location (Human Protein Atlas): Nucleoplasm
Pathways (Reactome):
Cell Cycle: Deposition of new CENPA-containing nucleosomes at the centromere
Gene Ontology:
Molecular function: protein binding; DNA binding; protein heterodimerization activity
Biological process: chromosome organization; chromosome segregation; kinetochore assembly; mitotic cell cycle; CENP-A containing chromatin assembly
Cellular component: chromosome, centromeric region; inner kinetochore; kinetochore; nuclear matrix; nucleoplasm; nucleus; nucleolus
Genetic constraint (gnomAD): Loss-of-function variants: 0 observed, 5.44 expected, observed/expected ratio (o/e) 0, 90% interval 0 to 0.55. That is too few expected variants to judge how well the gene tolerates losing a copy. Missense variants: 53 observed, 53.21 expected, observed/expected ratio (o/e) 1, 90% interval 0.8 to 1.25. Synonymous variants: 20 observed, 21.88 expected, observed/expected ratio (o/e) 0.91, 90% interval 0.64 to 1.33.
Homologues: Orthologues: chimpanzee CENPW (100% identical), macaque CENPW (91% identical), pig CENPW (82% identical), guinea pig CENPW (76% identical), dog CENPW (73% identical), mouse Cenpw (72% identical), rat Cenpw (72% identical), rat Cenpwl1 (68% identical), tropical clawed frog CENPW (44% identical).